NSD3 (nuclear receptor binding SET domain protein 3)
Diseases named in the same sentence as NSD3 in open-access papers (continued):
Sharing a sentence is not in itself a finding about the gene and the disease.
eosinophilia (1 paper, 2024). "Some extremely rare fusion genes, such as CSNK2A1::PDGFRB, CBFB::MYH11, and NSD3::NUTM1, have been identified in patients with eosinophilia using RNA−seq techniques." (PMID 38992589, 2024).
Lymphatic Metastasis (1 paper, 2025). Transfer of a neoplasm from its primary site to lymph nodes or to distant parts of the body by way of the lymphatic system. "Notably, NSD3 and POLD1 were highly mutated in patients with lymphatic metastasis compared to those without lymphatic metastasis." (PMID 39980551, 2025).
malignant peripheral nerve sheath tumor (1 paper, 2024). Malignant peripheral nerve sheath tumor (MPNST) is a rare and often aggressive soft tissue sarcoma occurring in a wide range of anatomical sites. "Here, we present a case of a 26-year-old man with a history of a multiply recurrent malignant peripheral nerve sheath tumor (MPNST) whose tumor was found to harbor an oncogenic NSD3::NUTM1 fusion." (PMID 39200173, 2024).
sarcoma (1 paper, 2024). A usually aggressive malignant neoplasm of the soft tissue or bone. "NSD3::NUTM1 fusions in sarcomas and their poorly understood biological implications necessitate a deeper examination of their oncogenic activity and clinical significance." (PMID 39200173, 2024). "Future research should focus on the development of specific inhibitors to target NSD3 fusion proteins in order to improve therapeutic outcomes for patients with such rare sarcomas." (PMID 39200173, 2024). "Our case also indicates that the NSD3 fusion partner can drive carcinogenesis and sarcoma genesis, with the resulting tumor phenotype most likely dependent on the originating cell type." (PMID 39200173, 2024). "Herein, we present a case of a 26-year-old man with an NSD3::NUTM1 fusion sarcoma." (PMID 39200173, 2024). "Additionally, it indicates that the NSD3::NUTM1 fusion can drive sarcoma genesis." (PMID 39200173, 2024). "In summary, our patient’s tumor is the first “MPNST” to show an NSD3::NUTM1 fusion, expanding the phenotypic profile of NUT fusion sarcomas." (PMID 39200173, 2024). "The NSD3::NUTM1 fusion has not been previously reported in a sarcoma." (PMID 39200173, 2024).
Sotos syndrome (1 paper, 2016). Sotos syndrome is a rare multisystemic genetic disorder characterized by a typical facial appearance, overgrowth of the body in early life with macrocephaly, and mild to severe intellectual disability. "Because of their high sequence similarities with NSD1, both the NSD2 and NSD3 genes were tested previously as potential candidates for NSD1-negative Sotos syndrome cases." (PMID 27834868, 2016).
cancer (52 papers, 2012 to 2026). A tumor composed of atypical neoplastic, often pleomorphic cells that invade other tissues. "More studies regarding the mutations found in NSD3 are necessary to identify the significance of these mutations on cancer progression." (PMID 38256018, 2024). "NSD3 overexpression has been associated with many cancers such as lung squamous cell carcinoma, squamous cell carcinoma of the head and neck, and AML as well as cancers of the bone, breast, colorectum, and pancreas." (PMID 39765675, 2024). "NSDs activation, including NSD1, NSD2, and NSD3 has been found to be tightly associated with the occurrence and progression of different cancer types." (PMID 39163297, 2024). "On top of its role as an oncogene in many diverse cancers, NSD3 is highly expressed in the brain and has been associated with AD and PD." (PMID 39765675, 2024). "Recent studies have shown that the cancer-associated NSD3 mutation, T1232A, presented with increased catalytic activity for H3K36 dimethylation (H3K36me2)." (PMID 34615858, 2021). "Intermolecular contacts between NSD3 and nucleosomes are altered by several recurrent cancer-associated mutations." (PMID 34440470, 2021). "NSD3 is mutated and hyperactive in some human cancers, but the biochemical mechanisms underlying such dysregulation are barely understood." (PMID 34440470, 2021). "Likewise, nonsense mutations in NSD3, such as, E1181K and T2342A, enhance the growth of cancer cells and xenograft tumors by disrupting an autoinhibitory loop in the NSD3 protein, thereby increasing enzymatic activity." (PMID 38256018, 2024). "Previously reported amplifications, mutations or fusion proteins involving NSD3 in cancer could be generated by this chromothripsis event." (PMID 38256018, 2024). "Also, we demonstrate that NSD3 variants are most prevalent among NSD genes across cancers we analyzed." (PMID 37062069, 2023). "Similarly, the equivalent E1181K and T1232A substitutions in NSD3 have also been linked with cancer and render NSD3 a more active enzyme." (PMID 37051671, 2023). "NSD3 is a principal 8p11-12 amplicon-associated oncogenic driver, whose overexpression and/or mutations are associated with malignant transformation and progression of multiple human cancers." (PMID 34615858, 2021). "This suggested that loss of NSD3 lead to apoptosis of cancer cells, suggesting that NSD3 may be a bona fide cancer driver gene." (PMID 24874471, 2014). "Furthermore, proteins, such as butyrophilin subfamily 1 member A1, keratin, type I cytoskeletal 10, HECT domain E3 ubiquitin protein ligase 3, nuclear receptor binding SET domain protein 3, and stomatin-like 2, were identified and implicated in cancer progression and prognosis." (PMID 40839607, 2025). "We hence propose NSD3L as a central epigenetic orchestrator of rRNA transcription in cancer and an enticing therapeutic target for the large group of cancers presenting with NSD3 amplifications and overexpression." (PMID 42082455, 2026). "Together, these findings highlight gain-of-function mutations in NSD family genes as critical epigenetic drivers of tumorigenesis, positioning NSD2 and NSD3 as promising biomarkers and therapeutic targets for cancer treatment." (PMID 41301842, 2025). "Among the NSD family members, NSD3 is most prominently dysregulated through gene amplification, leading to its overexpression in a variety of human cancers." (PMID 41301842, 2025). "Comprehensive analysis of The Cancer Genome Atlas (TCGA) datasets has identified NSD3 as a putative druggable cancer driver gene, showing recurrent amplification across multiple cancer types." (PMID 41301842, 2025). "A recent study further highlighted the key oncogenic role of NSD3 methyltransferase in LUSC, showing that NSD3 is a stronger cancer driver than FGFR1 within the 8p11-12 amplicon." (PMID 41301842, 2025). "The enhanced levels of NSD3 are known to stabilize c-Myc protein via protein–protein interaction in cancer cells." (PMID 39741006, 2025).
cancer (continued). "Among these, methyltransferase NSD3 encodes two splicing variants, NSD3-short (NSD3S) and NSD3-long (NSD3L) isoforms, which are frequently amplified in cancers." (PMID 39741006, 2025). "Given NSD3 has gained considerable attention in cancer development and progression, we decided to focus our efforts in understanding the role of NSD3 in hESC transformation." (PMID 39741006, 2025). "Altogether, these reports postulate NSD3 amplification as one of the main oncogenic drivers of the 8p11-12 amplicon across cancer types." (PMID 38256018, 2024). "With the exception of the singular H3K36me3-depositing SETD2, which appears to unambiguously function as a tumor suppressor, the remaining H3K36 methyltransferases (NSD1, NSD2, NSD3, and ASH1L) are all implicated in or associated with various cancers." (PMID 39403928, 2024). "Because of the 8p11-12 amplicon found in different epithelial cancers, NSD3 has been proposed, among other proteins, as an important oncogene for cancer progression." (PMID 38256018, 2024). "There is evidence that both the NSD3L and NSD3S isoforms are relevant for cancer progression, establishing NSD3 as a therapeutic target." (PMID 38256018, 2024). "The nuclear receptor-binding SET domain (NSD), a family of histone lysine methyltransferases, including NSD1, NSD2/WHSC1/MMSET, and NSD3/WHSC1L1, have been identified as potential therapeutic targets for cancer." (PMID 39163297, 2024). "The chromosomal location of NSD3 is frequently amplified across cancer types, such as breast, lung, and colon, among others." (PMID 38256018, 2024). "NSD3 has been postulated as one of the main oncogenic drivers of the amplicon 8p11-12 across cancer types." (PMID 38256018, 2024). "Due to the oncogenic activity of NSD3 isoforms, driven through the methyltransferase activity or acting as an adaptor protein, NSD3 has been studied as a therapeutic target in cancer." (PMID 38256018, 2024). "The pharmacological disruption of the BRD4-NSD3S complex is a novel therapeutic target that is currently underway, with further potential applications in various cancer types that rely on NSD3 activity." (PMID 38256018, 2024). "Given the importance that NSD3 has gained in the past few years in cancer development and progression, this article provides a detailed review of NSD3 alterations and involvement of the long and short isoform in important cancer pathways." (PMID 38256018, 2024). "The claudin-low/non-ER-negative/HER2-negative group had a higher prevalence than claudin-low/ER-negative/HER2-negative cancers of amplifications in loci 11q13.3, 17q12 and 8p11.23, encoding for the genes CCND1, ERBB2 and NSD3, respectively." (PMID 37345027, 2023). "As shown, the frequencies of genetic alterations in NSD1, NSD2, and NSD3 across cancers were 5%, 3%, and 7%, respectively." (PMID 37062069, 2023). "We interpret these findings to suggest that NSD3 is relevant to immune cell recruitment in cancer, and future studies would focus on the relevant cell types through which NSD3 mediates its functions in tumors." (PMID 37062069, 2023). "NSD3 is amplified in multiple cancer types, such as bladder, breast, lung, liver, and colorectal cancer, as well as head and neck cancer." (PMID 36360250, 2022). "Evidence has indicated that NSD3 has crucial effects on cancer cell proliferation and invasion via multiple signaling pathways." (PMID 35488336, 2022). "Nevertheless, the fact that the methylation of H3K36 plays such an important role in regulating enhancer activity and NSD3 is amplified in many cancers, suggests that NSD3 must play an important role in many different cellular processes." (PMID 34440470, 2021). "qRT-PCR assay results showed that NSD3 mRNA in cancer tissues was significantly higher than that in normal tissues from local patients." (PMID 34615858, 2021).
cancer (continued). "By catalyzing histone H3 methylation and interacting with different proteins, NSD3 has been proposed as an important oncogenic gene required for tumorigenesis and progression of human cancer." (PMID 34615858, 2021). "Results show that NSD3 mRNA expression in PDAC tissues (“Cancer”, N = 171) was significantly higher than that in the normal pancreatic tissues (“Normal”, N = 179)." (PMID 34615858, 2021). "Another feature of NSD3 is regarding to its genetic amplification in cancer cell lines of breast, which has been shown to be an important regulator of the cell cycle and probably participates in the invasion process of cancer cells." (PMID 32153656, 2020). "In this approach, some studies have already described important molecular alterations in the NSD1, NSD2 and NSD3 genes and their role in cancer initiation and development." (PMID 32153656, 2020). "NSD3 protein was detected by western blot in the four cancer cell lines, and the relative NSD3 protein levels positively correlated with NSD3 copy number, suggesting that NSD3 amplification leads to higher NSD3 protein levels." (PMID 24874471, 2014). "Our data suggest that NSD3 is a compelling drug target for cancer and that NSD1/NSD2/NSD3 structural similarity should be used for structure-based drug design to develop a new class of histone methyltransferase inhibitors for cancer." (PMID 24874471, 2014). "While the amplifications of SETDB1 and BRD4 have been previously identified and their roles in cancer have been well-studied, less is known about the functions of YEATS4 and NSD3 in cancer." (PMID 24874471, 2014). "Among the 73 cancer amplified genes we identified in this study, NSD3 was the most highly ranked gene in terms of putative cancer driver activity." (PMID 24874471, 2014). "The NSD family of HMTases comprised of three members (NSD1, NSD2/MMSET/WHSC1, and NSD3/WHSC1L) are oncogenes aberrantly expressed in several cancers, suggesting their potential to serve as novel therapeutic targets." (PMID 25494638, 2014). "To determine if the effects of NSD3 knockdown were due to changes in proliferation or cell survival, we measured the levels of apoptosis in cancer cells after NSD3 siRNA transfection using the Caspase Glo assay." (PMID 24874471, 2014). "Both the isoforms of NSD3 (NSD3L and NSD3S) are linked to cancer." (PMID 39741006, 2025). "Future studies investigating NSD3 inhibitors may clarify their potential as standalone therapies or as part of combination regimens with other anti-cancer agents, including immunotherapies, for the treatment of NSD3-overexpressing tumors." (PMID 40586874, 2025). "Particularly, NSD2 and NSD3 are frequently overexpressed in various cancers." (PMID 39741006, 2025). "NSD3 has also been shown to influence anti-tumor immune response across multiple cancer types." (PMID 40586874, 2025). "Moreover, in cancer the correlation between chromothripsis and NSD3-amplification (8p11-12 amplicon) was established in 2018." (PMID 38256018, 2024). "Compared to NSD1 and NSD2, NSD3 exhibits a higher genetic variation and amplification in cancer." (PMID 38256018, 2024). "NSD3 is present as three isoforms, with the NSD3L and NSD3S proteins being linked to cancer." (PMID 38256018, 2024). "Histones methyltransferase NSD3 targeting H3K36 is frequently disordered and mutant in various cancers, while the function of NSD3 during cancer initiation and progression remains unclear." (PMID 39119928, 2024). "Recently, this amplification has been correlated to a chromothripsis event, that could explain the different NSD3 alterations found in cancer." (PMID 38256018, 2024). "To further validate the results from TCGA databases, we collected five pairs of LUAD clinical samples and para‐carcinoma tissues to test the protein levels of NSD3 by Western Blot and immunohistochemistry (IHC), which confirmed that NSD3 was downregulated in LUAD tissue than in peritumoral tissue." (PMID 39119928, 2024).
cancer (continued). "Furthermore, compared to NSD1 and −2, we find that genetic variation and amplification to NSD3 is most prevalent in cancer." (PMID 37062069, 2023). "Nevertheless, our findings indicate that NSD3 may be informative for delineating clinical prognoses across multiple cancer types." (PMID 37062069, 2023). "Indeed, NSD3 is located in chromosome 8p11.2 and has been reported to be amplified in human primary cancers and in cells lines from cancers of the breast, pancreas, and lung." (PMID 37062069, 2023). "However, similar to the pattern of amplification observed in patient samples and cancer cell lines, FGFR inhibitor–sensitive PDX specimens had FGFR1/NSD3-centered amplification, whereas FGFR-deficient samples showed no clear center of amplification." (PMID 37606995, 2023). "In acute myeloid leukemia and acute lymphoblastic leukemia blood cancer, MS9715 could more effectively degrade NSD3, specifically inhibit the expression of c-Myc in cancer cells, and affect the growth of cells than BI-9321." (PMID 36770884, 2023). "This could explain why NUT::NSD3 fusion positive carcinomas outside the thorax appear to have a significantly better prognosis than their NUT::BRD4 positive counterparts." (PMID 37118352, 2023). "Epigenetic-based therapies are emerging as effective and valuable approaches in cancer and targeting NSD3 may indeed present a valuable approach." (PMID 34440470, 2021). "Importantly, as compared to WT NSD3, expression of NSD3-T1232A was more potent in augmenting cell viability, proliferation, migration, and invasion in koNSD3 cancer cells." (PMID 34615858, 2021). "NSD3 gene is located at chromosome 8p11.23, the locus with significant cancer relevance." (PMID 34615858, 2021). "Genomic alterations of NSD3 occur in multiple cancer types, implicating its cancer-promoting role." (PMID 34440470, 2021). "Moreover, NSD3 protein (long form, same for all figures) upregulation in cancer tissues was detected in four representative PDAC patients (namely, “Patient-1 to Patient-4”)." (PMID 34615858, 2021). "Additionally, we appointed the use of the NSD3 gene as a putative cancer driver gene in CRC once this gene harbours the highest rate of genetic amplification and it has correlation to mRNA expression." (PMID 32153656, 2020). "Additionally, we appointed the use of the NSD3 gene as a putative cancer driver gene in CRC given that this gene harbours the highest rate of genetic amplification." (PMID 32153656, 2020). "Finally, we reported that NSD3 showed the highest rate of gene amplification, which was highly correlated to its mRNA expression, a common feature of many cancer drivers." (PMID 32153656, 2020). "Overexpression of long or short NSD3 is capable of transforming a healthy into a cancer cell." (PMID 28903324, 2017). "It is very likely that the NSD3–NUT fusion may be critical for maintenance of MYC expression in these cancer cells." (PMID 28205554, 2017). "We evaluated the consequence of NSD3 depletion in cancer cells through siRNA knockdown." (PMID 24874471, 2014). "Interestingly, all four cancer cell lines exhibited apoptosis starting 24 hours after NSD3 siRNA transfection, and the relative apoptosis levels increased steadily after 48 and 72 hours post-transfection." (PMID 24874471, 2014). "Additionally, several NSD3 missense mutations, such as E1181K and T1232A, have been proposed to enhance the growth of cancer cells and xenograft tumors, through disruption of an auto‐inhibitory loop within the NSD3 protein product so as to augment its enzymatic function." (PMID 37062069, 2023). "Finally, the NSD3 gene presents elevated expression in many cancers such as lung and bladder." (PMID 32153656, 2020). "We found that the long isoform of the histone methyltransferase NSD3, NSD3L, one of the most frequently amplified genes in cancer, reshapes the chromatin environment surrounding ribosomal DNA (rDNA), thus triggering rRNA expression." (PMID 42082455, 2026).